ZCCHC2 (zinc finger CCHC-type containing 2)
Synonyms: C18orf49; KIAA1744; FLJ20281; FLJ20222
Tractability: PROTAC: ubiquitination databases record sites on it.
Gene: Protein-coding gene on chromosome 18 (62,523,025 to 62,587,709, forward strand). Ensembl gene ENSG00000141664.
Subcellular location (Human Protein Atlas): Nucleoli; Cytosol; Nucleoli rim; Nucleoplasm
Gene Ontology:
Molecular function: nucleic acid binding; phosphatidylinositol binding; zinc ion binding
Cellular component: cytoplasm
Genetic constraint (gnomAD): Loss-of-function variants: 28 observed, 68.87 expected, observed/expected ratio (o/e) 0.41, 90% interval 0.3 to 0.56. The upper end of that interval is the gene's LOEUF score, 0.56, which puts it in group 2 of 6, group 1 being the genes least tolerant of losing a copy. Missense variants: 1,369 observed, 1,335.6 expected, observed/expected ratio (o/e) 1.02, 90% interval 0.98 to 1.07. Synonymous variants: 653 observed, 558.63 expected, observed/expected ratio (o/e) 1.17, 90% interval 1.1 to 1.25.
Homologues: Orthologues: chimpanzee ZCCHC2 (99% identical), macaque ZCCHC2 (98% identical), dog ZCCHC2 (92% identical), pig ZCCHC2 (92% identical), mouse Zcchc2 (86% identical), rat Zcchc2 (85% identical), guinea pig ZCCHC2 (71% identical), rabbit ZCCHC2 (65% identical), tropical clawed frog zcchc2 (48% identical), zebrafish zcchc2 (23% identical), Drosophila melanogaster CG10492 (14% identical), Caenorhabditis elegans gls-1 (12% identical). Paralogues in human: ZCCHC14 (28% identical).
Diseases named in the same sentence as ZCCHC2 in open-access papers:
ZCCHC2 is named in the same sentence as 7 diseases in open-access papers, as found by Europe PMC text mining. Sharing a sentence is not in itself a finding about the gene and the disease. The quoted sentences say what the papers report.
retinoblastoma (2 papers, 2022 to 2023). A malignant tumor that originates in the nuclear layer of the retina. "ZCCHC2 has exhibited to inhibit retinoblastoma tumorigenesis by suppressing HectH9-mediated K63-linked polyubiquitination and activating c-Myc." (PMID 37679400, 2023). "For example, ZCCHC2 participates in the regulation of retinoblastoma tumorigenesis by suppressing the activity of c-Myc45." (PMID 35821031, 2022). "Knockout of ZCCHC2, on the other hand, promoted the proliferation of retinoblastoma cells." (PMID 37679400, 2023).
tumor (1 paper, 2022). "Moreover, transcripts relevant for cell division were regulated in Apoe−/−Neil3−/− cells, including upregulation of Zcchc2, which is reported to suppress tumorigenesis, and downregulation of Mlst8, deletion of which has been found to decrease tumor cell proliferation." (PMID 35079641, 2022).
ZCCHC2 also shares sentences with these, for which no sentence is quoted: acute lymphoblastic leukemia (1 paper); acute promyelocytic leukemia (1); chronic lymphocytic leukemia (1); lymphoma (1); malaria (1).